YAP1 (Yes1 associated transcriptional regulator)
Diseases named in the same sentence as YAP1 in open-access papers (continued):
Sharing a sentence is not in itself a finding about the gene and the disease.
tumor (continued). "Targeting YAP1 resulted in impaired viability and colony formation in human GC cell lines and suppressed tumor growth in carcinogen N-methyl-N′-nitro-N-nitrosoguanidine (MNNG)-induced and Helicobacter pylori (H. pylori)-associated GC models as well." (PMID 36289774, 2022). "In particular, YAP1 expression and tumor stiffness were significantly correlated in HR+ tumors and in tumors with non-collagenous stroma." (PMID 36291755, 2022). "YAP1 can show dual functions in tumorigenesis, either as an oncogene contributing to tumor development or as a tumor- suppressor gene suppressing carcinogenesis." (PMID 36591473, 2022). "MAOA promoted PCa metastasis by regulating downstream ROS and Twist1 pathways that mediated Shh/Gli signaling to activate YAP1 transcription in concert with AR to induce epithelial–mesenchymal transition and tumor–stromal cell interactions." (PMID 36452480, 2022). "YAP1 is a transcriptional coactivator capable of both oncogenic and tumor-suppressive activity depending on the tissue context." (PMID 35269556, 2022). "Another key signaling player in fibrosis and EMT is Yes-associated protein-1 (YAP1) along with transcriptional co-activator with PDZ-binding motif (TAZ), which are inhibited by the Hippo tumor suppressor pathway." (PMID 35053353, 2022). "NPC patients who developed metastasis had significantly higher levels of active YAP1 and FAPα in their tumor stroma, which was further correlated with tumor fibrosis and poorer metastasis-free survival." (PMID 35986369, 2022). "YAP1 pathway, which drives fetal conversion in the regenerating intestine, has consistently been recognized as a tumor promoter and inducer of CT resistance in cancer." (PMID 35606354, 2022). "Together, our findings verified the functional correlation between miR-335 and YAP1, and identified a new miR-335/KDM3A/YAP1 regulatory axis, which plays an important role in tumor growth and metastasis in ccRCC." (PMID 33888871, 2022). "We found that YAP1 expression positively correlates with tumor proliferation in almost all cancer types." (PMID 35685435, 2022). "YAP1 regulates EMT- and stem-cell-associated gene expression, which contributes to tumor progression, resistance to chemotherapy and metastasis." (PMID 35407556, 2022). "Inhibition of YAP1 phosphorylation using small-molecule inhibitors reduces tumor apoptotic capacity." (PMID 36532767, 2022). "As a result, ALKBH5-mediated YAP1 demethylation negatively regulates YAP1 translation and inhibits the growth of tumor cells in NSCLC." (PMID 35063010, 2022). "Taken together, these results suggest that YAP1 regulates the expression of multiple genes involved in angiogenesis through the mediation of E2F1 transcription factor in the tumor cells." (PMID 35937460, 2022). "Silencing YAP1 in CIC-deficient cells restores MAPK inhibitor sensitivity and suppresses tumor growth." (PMID 36198276, 2022). "Previous studies have revealed that YAP1 is up-regulated in different types of cancers, which is corrected with tumorigenesis and tumor progression." (PMID 35396377, 2022). "Further pharmacological studies with other TEAD binding molecules will be needed to determine the best profile for YAP1-TEAD inhibition in the different tumor types." (PMID 35689194, 2022). "Compelling evidence also showed that YAP1 can alter the TME by recruiting immunosuppressive cell types, suppressing cytotoxic T-cell function or promoting the polarization of tumor-associated macrophages towards the pro-tumor M2 phenotype." (PMID 36479120, 2022). "A few studies have reported YAP1 as a tumor suppressor in breast cancer, with high YAP expression associated with better survival outcomes." (PMID 35407556, 2022). "With our data placing YAP1 upstream of Notch signaling, we expected to detect YAP1 expression when Notch signaling is blocked in tumor sections from TKO;Rbpj mutant mice." (PMID 35577801, 2022).
tumor (continued). "Taken together, these data strongly suggests that YAP1-TEAD is a significant driver of tumor maintenance in Hippo-deregulated and YAP1 activated MPM tumors and highlights the attractiveness of this pathway for cancer therapy." (PMID 35689194, 2022). "Depletion of YAP1 suppressed cell proliferation, migration, and invasion but enhanced cell apoptosis in vitro and inhibited tumor growth in vivo." (PMID 36289774, 2022). "As to concern clinical and pathological correlations, NOTCH1, NEUROD1, MYCL1, and YAP1 were found significantly correlated with tumor stage." (PMID 36121500, 2022). "We confirmed that of the 137 TCGA cases for which RPPA data were available, cases with YAP1 amplification (8/37 C2 tumours and 6/100 C1 tumours) also showed increased YAP1 mRNA and protein expression." (PMID 36207323, 2022). "Nuclear YAP1 expression was evaluated by immunohistochemistry and tumor-infiltrating lymphocytes (TILs); tumor-stroma ratio (TSR) and stroma type of tumors were also evaluated." (PMID 36291755, 2022). "Quantitation of YAP1 interaction with HIF1α (red foci) clearly showed an increase in this interaction in RCC tumor tissues, where distribution of YAP1 was more nuclear than cytoplasmic." (PMID 35937460, 2022). "In the present study, we focused on the evaluation of YAP1 expression and tumor stiffness, which requires treatment-naïve whole tumor tissue for accurate and detailed microscopic evaluation." (PMID 36291755, 2022). "The potential role of YAP1 and its target genes in promoting tumor progression in clinical samples needs to be assessed." (PMID 35407556, 2022). "CircKRT17 knockdown increased the repressive effects of osimertinib on tumor growth in vivo by inhibiting YAP1 signaling." (PMID 36428672, 2022). "In this study, we performed IHC on whole tumor slides and set the H-score to 20 as the YAP1 positivity cut-off." (PMID 36291755, 2022). "The cooperation between Hedgehog and YAP1 signaling in tumor formation and progression remains to be uncovered." (PMID 36479120, 2022). "Inactivation of Capicua (CIC) or upregulation of yes-associated protein 1, YAP1, leads to broad RAS-RAF-MEK-ERK inhibitor resistance and tumor progression in multiple human cancers." (PMID 36198276, 2022). "Various studies have confirmed that metformin can sensitize tumour cells to antitumour drugs by inhibiting the expression level of YAP1." (PMID 35264157, 2022). "The YAP1-promoting tumor activity is probably attributed to the activation of TGF-β, Hedgehog, or KRAS signaling pathways." (PMID 36479120, 2022). "Second, TIMER was used to explore the relationship between YAP1 expression and tumor cell proliferation." (PMID 35685435, 2022). "We determined the H-score of nuclear YAP1 as intensity multiplied by the percent of positive tumor cells in the triplicates, and stratified patients accordingly." (PMID 35606354, 2022). "The knockdown of NEK2 played an anti-tumor role in vivo and was accompanied by a lower level and nucleus shuffling of YAP1." (PMID 35705994, 2022). "Recent studies demonstrated that VGLL4 exhibited tumor-suppressive roles in many cancer types, a process mainly depends on its competition with YAP1 for binding to TEAD." (PMID 36289774, 2022). "YAP1 is shown to mediate tumor-promoting functions such as stemness and epithelial-to-mesenchymal transition in mammary epithelial cell lines." (PMID 35407556, 2022). "The results showed that the weight and volume of the tumor were significantly decreased after wogonin treatment, while overexpression of YAP1 reversed this effect." (PMID 35037825, 2022). "It has been reported that MMP-2 plays a vital role in the process of tumor invasion which was regulated by YAP1." (PMID 35961957, 2022). "With enhanced stability and nuclear translocation, YAP1‐2 is more potent in promoting tumour invasion and metastasis than YAP1‐1." (PMID 35014181, 2022).
tumor (continued). "Together, our data strongly suggest that HK1EBV cell-derived exosomes mediate fibroblast activation through YAP1 activation and promote tumor progression." (PMID 35986369, 2022). "SNHG16 knockdown inhibited the colony formation, proliferation, migration, and invasion of CRC cells, and YAP1 overexpression rescued the effect of SNHG16 knockdown on tumor progression." (PMID 36147462, 2022). "IHC analyses showed the presence of active YAP1 in tumor cells and stromal fibroblasts and demonstrated FAPα immunoreactivity exclusively in stromal fibroblasts." (PMID 35986369, 2022). "Among all genes, four of them—NOTCH1, INSM1, YAP1, and NEUROD1—emerge as the most significant, being associated with both shorter disease-free interval and high tumor stage and/or risk of recurrence." (PMID 36121500, 2022). "Here we report for the first time a complete target validation study based on a multi-functional approach in which we clearly establish the importance of YAP1-TEAD for tumor maintenance in MPM." (PMID 35689194, 2022). "We analyzed the correlation between YAP1 expression and infiltration of 19 cell types in tumor tissues using CIBERSORT, Xcell, TIMER, EPIC, quanTIseq, and MCP-counter programs." (PMID 36479120, 2022). "Through profiling DNA methylome of individual tumor foci, we found that promoter methylation status of genes involved in detection of chemical stimulus, immune response, and Hippo/YAP1 pathway was significantly changed in mGBM." (PMID 34987659, 2022). "The YAP-1/Hippo signaling pathway regulates apoptosis and cell survival/proliferation and plays an essential role in mammalian organ size regulation and tumor suppression." (PMID 35846360, 2022). "To test the effect of CLP36 on YAP1 protein expression in vivo, we compared the levels of YAP1 in the mouse tumor tissues that express different levels of CLP36." (PMID 35836803, 2022). "Clinically, YAP1 and TAZ can be used as diagnostic and prognostic tools values as their upregulation is not only responsible for early tumor detection but also predicts a worse prognosis in patients suffering from GI cancers." (PMID 36289774, 2022). "The outcome of our analysis suggests that IL‐18 probably has anti‐cancer property on YAP1 overexpressed tumor cells which can be further clarified by in vitro studies." (PMID 34196131, 2022). "Detection of invadopodia by observing colocalization of TKS5, an invadopodia marker in human cancer lines, and cortactin in the sections of tumor tissue revealed that knocking out YAP1 expression significantly decreased invadopodia formation." (PMID 35773411, 2022). "YAP1 acts as an oncogene which promotes the tumor progression by targeting various signaling pathways." (PMID 35961957, 2022). "YAP1 is one of the most important regulators in the Hippo pathway, which is a novel tumor suppressor pathway." (PMID 34974798, 2022). "Our experiments have shown that the inhibitory role of miR-335 in cell proliferation, invasion, and migration relied on both KDM3A and YAP1, supporting the essential role of the miR-335/KDM3A/YAP1 axis in ccRCC tumor growth and metastasis." (PMID 33888871, 2022). "circCDYL has been observed to reduce apoptosis and increase tumor cell viability by miR-1180 binding, followed by an increase in YAP1 expression." (PMID 35673576, 2022). "In fact, YAP-1 knockout or inhibition was able to deactivate PSCs and severely reduce tumor proliferation." (PMID 35884592, 2022). "It has been shown that nuclear YAP1 levels positively correlate with tumor grade, metastasis and induction of CSC-like activity." (PMID 36210463, 2022). "YAP1 also seems to have a similar function as MDSCs in propagating tumor growth—it suppresses T-cell function and infiltration to the tumor microenvironment." (PMID 35189960, 2022). "Combination of an inhibitor of Yes-associated protein 1 (YAP1, a transcription factor which regulates cancer cell proliferation) and inRas37 showed a synergistic effect inRas37-sensitive tumor cell lines." (PMID 35892709, 2022).
tumor (continued). "We investigated the potential mechanism of YAP1 by which EBV product-containing exosomes dysregulate fibroblast function within the tumor microenvironment." (PMID 35986369, 2022). "We unveil an important link between IL‐18 and tumor‐derived enhanced YAP1, which leads to a gene expression profile toward tumor promotion profiling." (PMID 34196131, 2022). "There was a marked increase in the interaction of YAP1 with HIF1α in the tumor samples compared with normal tissues." (PMID 35937460, 2022). "Altogether, these findings indicate that SNHG16 can function as a miRNA sponge to directly bind and sequester endogenous miR-195-5p, thereby preventing it from inhibiting YAP1 expression and affecting tumor progression." (PMID 36147462, 2022). "(F, G) Representative sections of tumours derived from VillinCreERT2;Apcflox/+ (Apc+/- in F) or VillinCreERT2;Apcflox/flox (Apc-/- in G) immunostained for YAP1 (in red) and β-catenin (in green)." (PMID 35543624, 2022). "The tumor-promoting activity of YAP1 is attributed to the activation of TGF-β, Hedgehog, and KRAS signaling pathways." (PMID 36479120, 2022). "Inactivation of CIC increases YAP1 expression, which confers tumor growth, survival, and resistance to MAPK inhibitors." (PMID 36198276, 2022). "In the current study, we characterized the role for YAP1, a new tumor suppressor, in the resistance to chemo- and targeted therapy of FLT3-ITD+ AML cells through DNA damage repair." (PMID 35656547, 2022). "Nevertheless, the TEAD dominant negative approach showed that even transient downregulation of YAP1 and YAP1-TEAD target genes in vivo can lead to tumor growth inhibition in established tumors." (PMID 35689194, 2022). "Consistent with our in vitro findings, we found that YAP1 depletion increased tumor volume and weights." (PMID 35930163, 2022). "Taken together, our results unraveled that LIN28 inhibited Hippo pathway via recruiting MSI2 and de-stabilizing the mRNA transcript of YAP1 upstream kinases in TNBC cells, thereby enhancing CSC-associated properties, tumor cell growth and metastasis." (PMID 35102250, 2022). "There was a paucity of amplifications and a YAP1- amplification in the tumor of patient 23 was the only oncogene-amplification detected in the cohort (online resource)." (PMID 34967922, 2022). "In particular, we confirmed that KIT‐targeting drugs, such as pazopanib, are potentially adequate to target POU2F3‐driven SCLCs, whereas YAP1‐driven tumours are more resistant to vorinostat (targeting HDAC1)." (PMID 36149789, 2022). "We confirmed that K-975 inhibited MPM tumor growth in vivo and modulated YAP1-TEAD dependent gene transcription, similar to what we had observed when using a genetic knockdown of YAP1." (PMID 35689194, 2022). "In keeping with these observations, we confirmed strong nuclear localization of YAP1, as well as weaker cytoplasmic labelling in our patient’s tumor by immunohistochemistry." (PMID 35986430, 2022). "Colony formation, CCK8, Transwell, and wound healing assays revealed that YAP1 overexpression significantly promoted tumor progression, whereas the promotive effect on HCT116 was impaired by simultaneous knockdown of SNHG16." (PMID 36147462, 2022). "The conditional downregulation of YAP1 in established tumor xenografts leads to the inhibition of YAP1-dependent gene transcription and eventually tumor regression." (PMID 35689194, 2022). "The effect of YAP1 downregulation on tumor growth was first tested in vitro using a genetic approach based on a TEAD dominant-negative (TEAD2-DN) construct." (PMID 35689194, 2022). "We observed, that YAP1 knockdown not only stopped tumor progression, but lead to massive tumor regression in vivo." (PMID 35689194, 2022). "The YAP1 mRNA expression level in the tumor tissues of 64 CMM patients was determined to be 1.264 ± 0.105." (PMID 33996543, 2021).
tumor (continued). "The transcription factor YAP1, a major effector of the tumor suppressive Hippo signaling pathway, is necessary to maintain pluripotency in embryonic stem cells." (PMID 34199594, 2021). "In recent years, YAP1 has been reported to participate in Epithelial-to-mesenchymal transition (EMT) process of tumor cells." (PMID 34094936, 2021). "After 3-day treatment at 30 mg/kg PO in immunodeficient mice bearing NCI-H226 tumors, I-27 led to >50% downregulation of CTGF mRNA in the tumor, a known transcriptional target of YAP1–TEAD." (PMID 34685695, 2021). "Overexpression of YAP1 contributes to aggressiveness in several tumor types by inducing proliferation, aggressiveness, tumor initiation, and stemness." (PMID 34944872, 2021). "Recent evidence indicated that PTC tumor spheres transfected with siRNA targeting YAP1 had less differentiation potential." (PMID 33904381, 2021). "If CBX4 and YAP1 are both inhibited, the best anti-tumour effect is achieved in vitro and in vivo, particularly in SR cells." (PMID 33473171, 2021). "The hippo-YAP1 axis, known as a tumour suppressor pathway, also plays an important role in cell proliferation and apoptosis." (PMID 34082774, 2021). "Direct upregulation of PD-L1 transcripts in tumor cells by both YAP1 and TAZ has been shown in multiple contexts and involves their interaction with TEAD transcription factors." (PMID 34685695, 2021). "The SRC tyrosine kinase activates YAP1 and thereby drives tumor onset, growth, progression and metastasis." (PMID 34831091, 2021). "These 9 protein binding modules allow selective interactions with a wide range of effectors, including the PTEN tumor suppressor, the β-catenin and YAP1 proto-oncogenes, and the regulation of the PI3K/AKT, the Wnt, and the Hippo signaling pathways." (PMID 34503076, 2021). "For malignant mesothelioma tumors, it has been shown that the aberrant activation of YAP1 is an actual driver of tumor maintenance." (PMID 34685695, 2021). "Knockdown of YAP1 did remarkably inhibit the xenograft tumor growth, accompanied by the reduction of c-Myc-stained positive cells and the induction of senescent cells as determined by the SA-β-gal staining using frozen sections." (PMID 33495462, 2021). "Since the Hippo-YAP axis is known as a tumor suppressor pathway, let-7a also inhibits cell proliferation, and let-7a affects the expression of YAP1 and TAZ." (PMID 34082774, 2021). "Unsurprisingly, overexpression of LTBP4 increased the expression of LTBP4, cleaved caspase-3, and N-cadherin, but inhibited that of Ki67, E-cadherin, and YAP1 in tumor tissues of mice." (PMID 35252214, 2021). "The results showed that activation of Hippo/YAP1 signaling contributes to the GABABR1 down-regulation increased tumor growth in vivo." (PMID 34131398, 2021). "Previous studies pointed out that the low level of YAP1 in hematologic cancers suppressed the DNA damage-induced apoptosis, facilitating tumor cell survival." (PMID 35059315, 2021). "MiR-205 is another tumor suppressive molecule that targeted the action of both YAP1 and VEGFA and inhibited cell proliferation, cell cycle progression, and angiogenesis." (PMID 35186709, 2021). "In transgenic mice, tissue-specific expression of YAP1 results in tissue overgrowth and tumor formation." (PMID 34206989, 2021). "Immunohistochemical (IHC) staining showed that the expression levels of Ki67 and YAP1 in xenograft tumor tissues of nude mice injected with sh-MALAT1-transfected cells were markedly downregulated." (PMID 34761116, 2021). "YAP1 activation is also a major resistance mechanism in other tumor indications with increased MAPK pathway signaling." (PMID 34685695, 2021). "The Hippo pathway is a tumor-suppressive cellular signaling pathway that regulates proliferation and cell survival via negative regulation of YAP1 stability and nuclear translocation." (PMID 34373451, 2021).